PER2 (period circadian regulator 2)
Diseases named in the same sentence as PER2 in open-access papers (continued):
Sharing a sentence is not in itself a finding about the gene and the disease.
colon carcinoma (6 papers, 2013 to 2024). "In a colon cancer, it was observed that the loss of PER2 expression was associated with a lower ratio of CAFs infiltration, resulting in a reduced metastasis rate." (PMID 38607733, 2024). "Contrary, the downregulation of β-catenin by siRNA increases the PER2 protein level in human colon cancer cells and in small intestine mucosa of mice with APC mutations (APCMin/+)." (PMID 28220106, 2017). "Down-regulation of Per2 increases beta-catenin protein levels and its target cyclin D, leading to cell proliferation in colon cancer cell lines and colonic polyp formation." (PMID 25414671, 2014). "Increased beta-catenin affects the circadian clock and enhances PER2 protein degradation in colon cancer." (PMID 25414671, 2014). "One study found that Cry1 and other circadian gene (Cry2, Per2 and BamlI) mRNA expression levels were similar in colon cancer and adjacent normal mucosa." (PMID 23626715, 2013). "Moreover, the β-catenin expression is increased following Per2-silencing in HRECs, in agreement with previous studies performed on colon carcinoma cells." (PMID 27662578, 2016). "Since we found that PER1 was the most significant downregulated genes when PER2 expression is low, the process may be related ATM/CHK2 as reported in a human colon cancer cell line." (PMID 33810377, 2021). "In addition to stromal cells, the dysfunction of PER2 within non-cell stromal components also curtailed tumor growth in breast and colon cancer." (PMID 38607733, 2024).
delirium (6 papers, 2016 to 2025). A disorder characterized by confusion; inattentiveness; disorientation; illusions; hallucinations; agitation; and in some instances autonomic nervous system overactivity. "Relative risk to develop delirium was 2.92 (95% CI 1.15–4.64) for patients with high PER2 and 2.40 (95% CI 1.18–5.07) for patients high HO1 expression." (PMID 34321570, 2021). "Some have tested the functional role of the circadian rhythm protein Phase 2 (PER2) in different mouse models similar to delirium." (PMID 40672459, 2025). "Delirium resulted in overall disruption of core clock genes in mouse hippocampus, including E4bp4, Bmal1, Rev‐erbα, Cry1, and Per2." (PMID 35713240, 2022). "In this study, the patient group that showed clinically manifest delirium over the first week of ICU treatment had comparatively lower Per2 expression levels in the CSF on day 1 after SAH." (PMID 33562664, 2021). "With regard to delirium, increasing PER2 expression has been shown to be effective against midazolam-induced delirium in mice." (PMID 34321570, 2021). "When dividing patients into categories of high and low mRNA expression in relation to ISS scoring, delirium (nuDesc > 1) was significantly more frequent in patients within the group of high PER2 (P = 0.032) and HO1 (P = 0.019) expression." (PMID 34321570, 2021). "High expression levels increased the odds of delirium occurrence (PER2: OR = 4.32 [1.14–13.87]; HO1: OR = 4.50 [1.23–14.42])." (PMID 34321570, 2021). "Correlation of delirium and PER2 expression remained significant 1 week post trauma (r = 0.366, P = 0.024, r2 = 0.083, P = 0.048)." (PMID 34321570, 2021). "In animal models, constant light exposure, inflammation, and midazolam exposure can induce delirium-like phenotype (i.e., impaired executive and memory function) and reduced expression of PER2 in the SCN." (PMID 33573430, 2021). "Moreover, we examined the effects of Per2 deletion (a genetic model of circadian disruption) on the development of delirium." (PMID 35713240, 2022). "Expression levels of PER2 and HO1 correlate with the incidence of delirium in an age-independent manner and may potentially improve diagnostic algorithms when used as delirium biomarkers." (PMID 34321570, 2021). "As Per2 expression in the CSF overall was suppressed in comparison to controls, this could indicate that higher CSF Per2 expression results in lesser circadian rhythm disruption and thus lower incidence of delirium." (PMID 33562664, 2021). "This delirium-like phenotype was abolished by the PER2 enhancer nobiletin." (PMID 33573430, 2021). "On a descriptive statistical level limited by our patient cohort, our data suggest that TBI and high PER2 expression may be favorable for survival, while high HO1 expression, high bilirubin, delirium and AKI carried a greater risk of death." (PMID 34321570, 2021). "We studied a sub-group of patients with TBI and measured PER2 and HO1 mRNA expression and asked if expression correlated with subjects developing delirium and/or AKI." (PMID 34321570, 2021). "Blood leukocyte Per2 expression levels were largely equal in patient subgroups with or without delirium (day 1 after SAH vs. delirium week 1: p = 0.967, n = 40, day 7 after SAH vs. delirium week 2: p = 0.274, n = 29)." (PMID 33562664, 2021). "This study found a possible association between the extent of early Per2 suppression after SAH and early delirium incidence, delayed cerebral ischemia and mortality, but not with functional neurological outcome." (PMID 33562664, 2021). "Utilizing expression of PER2 and HO1 as biomarkers could potentially improve diagnosis algorithms for delirium by adding an objective laboratory parameter." (PMID 34321570, 2021). "Our data suggests that PER2 and HO1 mRNA expressions may prospectively assess delirium and trauma severity." (PMID 34321570, 2021). "Here, we hypothesized that PER2 and HO1 expression could serve as potential serum biomarkers to diagnose and predict delirium and/or AKI." (PMID 34321570, 2021).
delirium (continued). "However, each of these associations remained non-significant (TBI: P = 0.609, high PER2: P > 0.999, high HO1: P > 0.999, high bilirubin: P = 0.103, delirium: P = 0.286, AKI: P = 0.071)." (PMID 34321570, 2021).
hepatoma (6 papers, 2011 to 2025). "Next, we assessed the regulatory effects of Per2 on CYP2B10 expression in mouse Hepa-1c1c7 hepatoma cells by performing overexpression and knockdown assays." (PMID 34887762, 2021). "Using an in vitro HCV infection system, HCV core protein (genotype 1b) decreased PER2 and CRY2 protein levels in infected HuH-7 cells (human hepatoma cell line), whereas overexpression of Per2 in HuH-7 cells reciprocally decreased HCV RNA replication." (PMID 34512600, 2021). "To test whether low dose of palmitate (50 ~ 100 μM) affects the molecular clock function in hepatocytes, we examined the effect of palmitate treatment on the activity of a mouse Per2 promoter-driven luciferase reporter (Per2-luc) in a mouse hepatoma Hepa1c1c-7 (Hepa1) cell line." (PMID 26075729, 2015).
lymph node metastasis (6 papers, 2014 to 2021). "PER2 expression is also decreased in squamous cell carcinoma and decreased PER2 expression is associated with advanced clinical stage, lymph node metastasis, and unfavorable patient survival." (PMID 34069297, 2021). "Similar observations have been pointed out by Kuo et. al., who have found that homogeneous expression of PER2 was associated with lymph node metastasis and a poor prognosis." (PMID 29958276, 2018). "Furthermore, the low expression of PER-2 is reportedly negatively linked to poor differentiation, big tumor sizes, high TNM stage, and lymph node metastasis in NSCLC patients; the overexpression of PER-2 inhibits the migration and invasion of NSCLC cell lines." (PMID 33752691, 2021). "Furthermore, the heterogeneity among studies related to low Per2 expression and lymph node metastasis was obviously decreased in non-gastrointestinal cancer group (OR=3.89, 95%CI: 2.59∼5.84, Ρ<0.001, Ι2=1.4%, Ρ=0.363)." (PMID 32437452, 2020).
migraine (6 papers, 2018 to 2023). "A good candidate is PER2, which is already a known cause of FASPS; it is however unknown whether PER2 mutation carriers also have an increased risk for migraine." (PMID 32503413, 2020). "Further details of its role in migraine are to be elucidated, but CKIδ is a ubiquitous serine-threonine kinase that phosphorylates the circadian clock protein PER2, as well as other proteins involved in brain signalling." (PMID 31226929, 2019). "Thus this loss of function mutation that co-expresses altered circadian phases and migraine with aura indirectly highlight a potential relationship between PER2 regulation and migraine." (PMID 29508090, 2018). "This hypothesis may be supported by the result showing that migraines with or without aura were connected to a mutation in the casein kinase Iδ gene (CKIδ) (with phosphorylating effect on the Per2 circadian protein) in two families with advanced sleep phase syndrome." (PMID 31534960, 2019).
asthma (5 papers, 2016 to 2025). "The disease–gene association p-value scores (−1og10) in moderate asthma-related genes ranged from 3.2 (ZNF862) to 6 (PER2), while in severe asthma-related genes, it varied from 2.2 (TMCC1) to 6 (SLCO1B3, and WNK4)." (PMID 32512817, 2020). "There was a significant increase in the expression of PER3 at 22:00 h (p<0.05) and PER2 at 04:00 h (p<0.05) in asthma compared to healthy samples." (PMID 37404842, 2023). "PER2 had a high significance in the moderate-to-severe asthma dataset." (PMID 32512817, 2020). "PER2 (adjusted p = 0.003) and PER3 (adjusted p = 0.002) expressions were statistically higher in the blood samples of asthma patients." (PMID 37108640, 2023). "In our analysis, among the seven core clock genes, we found only PER2 and PER3 have a slightly but significantly higher expression in the blood samples from asthma patients." (PMID 37108640, 2023). "Overall, there was more variation in the expression of PER2, PER3 and NR1D1 at later time points (16:00 h and 22:00 h) compared to morning time points (04:00 h and 10:00 h) in asthma compared to health." (PMID 37404842, 2023). "Ehlerset al. showed a reduction in expression of BMAL1, PER2 and NR1D1 in bronchial brushings from mild/moderate asthma patients; however, only a single time point was evaluated." (PMID 37404842, 2023). "In line with our results, PER2 and PER3 were increased, most noticeably when collected between 4 pm and 9 pm for PER2 and between 9 am and 9 pm for PER3, in peripheral blood mononuclear cells from asthma patients (unpublished results, scientific meeting abstracts)." (PMID 37108640, 2023).
glioblastoma (5 papers, 2021 to 2025). The most malignant astrocytic tumor (WHO grade IV). "In summary, LbGP may upregulate the expression of PER2 to reduce the expression of SREBP1c, inhibit lipid synthesis in glioblastoma, and inhibit glioblastoma cell proliferation." (PMID 37069338, 2023). "To further probe the role of the circadian clock in treatment response, we generated CRISPR-Cas9 knockouts (KOs) of three key clock components—BMAL1, PER2, and NR1D1—in the T98G glioblastoma cell line." (PMID 41387951, 2025). "Western blot results showed that the glioblastoma samples had high FASN and SREBP1c expression and low PER2 expression." (PMID 37069338, 2023).
non-small cell lung carcinoma (5 papers, 2017 to 2022). A group of at least three distinct histological types of lung cancer, including non-small cell squamous cell carcinoma, adenocarcinoma, and large cell carcinoma. "Similarly, in non-small cell lung cancer, Per2 overexpression inhibits proliferation, migration, invasion, and cell cycle progression." (PMID 35599595, 2022). "Similar to the results in non-small-cell lung cancer, PER2 overexpression significantly inhibited the proliferation, migration, and invasion of OSCC cells, indicating that PER2 might act as a crucial antitumor gene." (PMID 32185221, 2020).
Sepsis (5 papers, 2012 to 2025). Sepsis is defined as life-threatening organ dysfunction caused by a dysregulated host response to infection. "In a study on circadian rhythms in patients with sepsis, it was suggested that sepsis suppresses the expression of the Circadian gene, such as CRY1, REV-ERBα, NR1D2, DBP, and PER2." (PMID 39097582, 2024). "In sepsis patients, the severity of the inflammatory process is directly related to the degree of change in the clock genes BMAL1 and PER2." (PMID 33900485, 2021). "As clock genes, PER2, PER3, and CRY1 may be markers of sepsis severity." (PMID 40362233, 2025). "It is also not clear why there was a significant effect of prior sepsis on PER2, but not PER1 in the SCN, although modulation through different signalling mechanisms may be a factor here." (PMID 23071720, 2012).
Abdominal obesity (4 papers, 2021 to 2024). Excessive fat around the stomach and abdomen. "In a Spanish population, the G allele in the PER2 rs2304672 SNP and the TT genotype in the PER2 rs4663302 SNP were associated with a greater probability of withdrawal from dietary treatment for abdominal obesity." (PMID 37761843, 2023). "In addition, since PER2 exerts biological effects on multiple systems, the c.1403G>A:p.(Arg468Gln) variant might also be involved in the development of phenotypes other than IH, such as central obesity, of this patient." (PMID 33827678, 2021).
alcohol (4 papers, 2010 to 2022). "Among the severely alcoholic females, our results suggest the PER2 G allele as a possible risk factor for alcoholism." (PMID 20187847, 2010). "The second is a potential sex difference with regard to the association between the PER2 10870 polymorphism and alcoholism." (PMID 20187847, 2010).
chronic lymphocytic leukemia (4 papers, 2017 to 2023). "In chronic lymphocytic leukemia, the ratio of PER2 to CRY1 is suggested to be a prognostic marker that predicts survival outcomes of patients, with a low PER2:CRY1 having the best outcomes." (PMID 33089179, 2019). "Down-regulation of the core circadian genes BMAL1 and Per2 have previously been reported in patients diagnosed with chronic lymphocytic leukemia (CLL)." (PMID 30210557, 2017). "For example, the circadian oscillation of gene expression is aberrant in leukemic cells, as BMAL1, PER1, and PER2 are down-regulated in patients with chronic lymphocytic leukemia." (PMID 28487473, 2017).
endothelial dysfunction (4 papers, 2020 to 2025). In vascular diseases, endothelial dysfunction is a systemic pathological state of the endothelium (the inner lining of blood vessels) and can be broadly defined as an imbalance between vasodilating and vasoconstricting substances produced by (or acting on) the endothelium. "Per2 mutations are related to early vascular senescence, limb ischaemia and endothelial dysfunction." (PMID 32426819, 2020). "Furthermore, Per2, which was increased by Dox and also increased by advanced tumor disease, is associated with endothelial dysfunction and AKT-dependent senescence." (PMID 34669013, 2021). "When subjected to hind‐limb ischemia, Per2 mutant mice presented decreased blood flow and developed autoamputation in the distal limb, indicating that Per2 deficiency could significantly impair endothelial cell function and accelerate vascular senescence, thus leading to endothelial dysfunction." (PMID 41143275, 2025).
esophageal cancer (4 papers, 2016 to 2024). A primary or metastatic malignant neoplasm involving the esophagus. "One of the novel points of the present data is that Per2 expression is negatively associated with the decrease in E-cadherin expression in esophageal cancer cells." (PMID 26898709, 2016). "The present data show that the levels of Per2 are markedly high in esophageal cancer with metastasis, implying such an unusual expression of Per2 may be associated with esophageal cancer metastasis; the underlying mechanism needs to be further investigated." (PMID 26898709, 2016). "Since cancer progression is associated to reduced BMAL1 and PER2 oscillations, it will be important to determine whether more malignant esophageal cancer epithelial cells are characterized by additional modifications of clock related genes and how the circadian clock is impacted." (PMID 33810377, 2021). "In cervical and esophageal cancer, overexpression of PER2 suppressed cell proliferation and activation of REV-ERBα and RORα resulted in cancer cell death." (PMID 37968308, 2023). "In the same line, our results clearly indicate that cisplatin treatment of esophageal cancer cells is more efficient when PER2 expression is low." (PMID 33810377, 2021). "To determine the impact of PER2 oscillations on esophageal cancer cells, we have synchronized the KYSE-410 cells using dexamethasone and profiled the cells when PER2 expression is high or low (24 and 36 h after synchronization respectively)." (PMID 33810377, 2021). "Strikingly, treating esophageal cancer cells with cisplatin for 4 h when PER2 expression is high or low has different outcomes." (PMID 33810377, 2021). "It will be important to investigate the molecular mechanisms that link PER2 expression, DNA damage and apoptosis in esophageal cancer cells." (PMID 33810377, 2021). "Here, we characterized the consequences of the daily oscillations of the clock-related gene PER2 in esophageal cancer cells and found that chemotherapy is more efficient when PER2 expression is low." (PMID 33810377, 2021). "Characterization of esophageal cancer cells by RNAseq indicated that when PER2 expression is low, several transcripts related to the apoptotic signaling pathway are upregulated." (PMID 33810377, 2021). "Overexpression of Per2 markedly increased the migratory capacity of esophageal cancer cells, which was abolished by the inhibition of HDAC1." (PMID 26898709, 2016). "The present data provide further evidence that overexpression of Per2 promotes the migratory capacity of esophageal cancer cells." (PMID 26898709, 2016). "We wondered if the overexpression of Per2 promoted a role in the up regulation of the E-cadherin repressors in esophageal cancer cells." (PMID 26898709, 2016). "Our data show a novel aspect of Per2 expression in esophageal cancer that high levels of Per2 were detected in the cancer tissue of metastasis." (PMID 26898709, 2016). "To test the inference, we overexpressed the Per2 in Eca109 cells and CP-C cells (Two esophageal cancer cell lines), which markedly repressed the expression of E-cadherin in the esophageal cancer cells." (PMID 26898709, 2016). "The results showed that higher levels of pHDAC1 were detectable in wild esophageal cancer cells, which was markedly increased in the Per2-overexpressing esophageal cancer cells." (PMID 26898709, 2016). "We next took a further insight into the mechanism by which Per2 modulating the gene transcription of E-cadherin in esophageal cancer cells." (PMID 26898709, 2016). "This study aims to investigate the role of one of the circadian proteins, period-2 (Per2) in repressing the expression of E-cadherin in esophageal cancer (esophageal cancer)." (PMID 26898709, 2016). "We wondered if HDAC1 was involved in the Per2-repressed E-cadherin expression in esophageal cancer cells." (PMID 26898709, 2016).